TMEM176B (transmembrane protein 176B)
Diseases named in the same sentence as TMEM176B in open-access papers (continued):
Sharing a sentence is not in itself a finding about the gene and the disease.
chronic obstructive pulmonary disease (1 paper, 2024). A chronic and progressive lung disorder characterized by the loss of elasticity of the bronchial tree and the air sacs, destruction of the air sacs wall, thickening of the bronchial wall, and mucous accumulation in the bronchial tree. "A recent study suggested a potential role for TMEM176B in the pathogenesis of chronic obstructive pulmonary disease (COPD), a common lung condition that shares some common pathological features with pulmonary fibrosis." (PMID 39170226, 2024).
colon cancer (1 paper, 2019). "High stromal TMEM176B expression in colon cancer was associated with significantly lower overall patient survival." (PMID 31085177, 2019).
glioma (1 paper, 2022). A benign or malignant brain and spinal cord tumor that arises from glial cells (astrocytes, oligodendrocytes, ependymal cells). "In conclusion, MS4A4A, MS4A4E, MS4A6A, MS4A7, TMEM176A, and TMEM176B may act as potential diagnostic or prognostic biomarkers in glioma and play a role in forming the immune microenvironment in gliomas." (PMID 35734424, 2022). "In TCGA data, the expression level of MS4A4A, MS4A4E, MS4A6A, MS4A7, TMEM176A, and TMEM176B in IDH wild-type glioma was elevated." (PMID 35734424, 2022). "The Cox proportional hazards regression model indicates TMEM176A and TMEM176B expressions in tumor cells are independent prognostic indicators of glioma." (PMID 35734424, 2022). "To further analyze the cellular function of TMEM176B, we have successfully established the TMEM176B-knockdown glioma cell lines and explored the effect of TMEM176B on cell function." (PMID 35734424, 2022). "In conclusion, these results demonstrated that the knockdown of TMEM176B protein inhibited the proliferation and migration of glioma cells." (PMID 35734424, 2022). "In brief, these findings suggest that TMEM176A and TMEM176B are prognosis-related biomarkers in glioma." (PMID 35734424, 2022). "Using bioinformatics analysis methods based on the data from public databases, we found that the expression of MS4A4A, MS4A4E, MS4A6A, MS4A7, TMEM176A, and TMEM176B was significantly overexpressed in glioma tissues compared with that of normal tissues." (PMID 35734424, 2022). "Therefore, these preliminary results indicate that MS4A4A, MS4A4E, MS4A6A, MS4A7, TMEM176A, and TMEM176B are potential prognostic factors for glioma." (PMID 35734424, 2022). "TMEM176B was highly expressed in various glioma cell lines (U251 and LN229)." (PMID 35734424, 2022). "Knockdown of TMEM176B suppresses malignant properties of glioma cells." (PMID 35734424, 2022). "Moreover, the C-index values for the prediction model of TMEM176A and TMEM176B were 0.832 and 0.833, indicating a moderate predictive accuracy for OS in glioma." (PMID 35734424, 2022). "Finally, we screened out TMEM176B, which is overexpressed in glioma and significantly correlated with the prognosis of glioma patients." (PMID 35734424, 2022). "Finally, data from the cell culture suggested that knockdown of the TMEM176B gene contributes to the decreased proliferation and migration of glioma cells." (PMID 35734424, 2022). "We found that TMEM176A expression in tumor cells and TMEM176B expression in tumor cells, age, WHO grade, and IDH status were independent prognostic factors in glioma." (PMID 35734424, 2022). "In TCGA data, the expression level of MS4A4A, MS4A4E, MS4A6A, MS4A7, TMEM176A, and TMEM176B in 1p/19q non-codel glioma was elevated." (PMID 35734424, 2022).
hepatocellular carcinoma (1 paper, 2024). A malignant tumor that arises from hepatocytes. "In hepatocellular carcinoma (HCC) tissues, the transcription of the 5’ and 3’ introns of the gene that encodes human TMEM176B is significantly reduced." (PMID 39717774, 2024).
lung diseases (1 paper, 2024). "The role of TMEM176B in lung diseases has been a topic of considerable interest in recent scientific literature." (PMID 39170226, 2024). "In the context of lung diseases, the functional significance of TMEM176B is not fully understood yet." (PMID 39170226, 2024).
lung squamous cell carcinoma (1 paper, 2024). "Using transcriptome sequencing and conducting enrichment analysis demonstrated an association between TMEM176B and the differentiation of lung squamous cell carcinoma (GO:0030154)." (PMID 39001509, 2024).
lymph node metastasis (1 paper, 2024). "The multivariate Cox regression analysis identified lymph node metastasis (p = 0.033) and TMEM176B expression (p = 0.009) as independent prognostic OS determinants in the GC cohort." (PMID 38438907, 2024). "The univariate Cox regression analysis demonstrated significant correlations between overall survival (OS) and lymph node metastasis (p = 0.005), TNM staging (p = 0.039), and TMEM176B expression (p = 0.001) in the GC cohort." (PMID 38438907, 2024).
migraine (1 paper, 2025). "Five genes were replicated both in the migraine dataset and in IBD-Character: TMEM176A, TMEM176B, PI3, HIST1H2BD, and HIST1H2AD." (PMID 41010012, 2025).
multiple sclerosis (1 paper, 2022). A progressive autoimmune disorder affecting the central nervous system resulting in demyelination. "In multiple sclerosis, TMEM176B has been reported as a member of the gene expression signature." (PMID 36340035, 2022). "In particular, the A134T genetic variant of TMEM176B could be associated with multiple sclerosis although this has not been formally proven." (PMID 36340035, 2022).
pancreatic cancer (1 paper, 2023). "TMEM176B inhibits NLRP3 inflammasome activation to regulate adaptive and innate antitumor responses, suggesting that TMEM176 may be a potential immunotherapy target for pancreatic cancer." (PMID 37265785, 2023).
pulmonary fibrosis (1 paper, 2024). Chronic progressive interstitial lung disorder characterized by the replacement of the lung tissue by connective tissue, leading to progressive dyspnea, respiratory failure, or right heart failure. "This comparison aimed to confirm the downregulation of TMEM176B in pulmonary fibrosis, as initially observed." (PMID 39170226, 2024). "Given the existing data, there is a significant gap in our understanding of the role of TMEM176B in pulmonary fibrosis." (PMID 39170226, 2024). "It is this gap that our study seeks to address, specifically investigating the role and impact of TMEM176B on the TGFβ1-SMAD signaling pathway in the context of pulmonary fibrosis." (PMID 39170226, 2024). "In an endeavor to further clarify the expression profile of TMEM176B in human pulmonary fibrosis tissues, we measured the mRNA expression levels of TMEM176B in pulmonary tissues from both healthy individuals and those with pulmonary fibrosis." (PMID 39170226, 2024). "The mechanism by which TMEM176B mitigates pulmonary fibrosis appears to be related to the inhibition of the TGFβ1-SMAD signaling pathway." (PMID 39170226, 2024). "Our observations during the experimental induction of pulmonary fibrosis in mice further reinforced its potential role - we consistently observed a marked decrease in TMEM176B expression." (PMID 39170226, 2024). "Mechanistically, TMEM176B appears to mitigate pulmonary fibrosis by inhibiting the TGFβ1-SMAD signaling pathway, which is a critical mediator of fibroblast proliferation and differentiation and promotes extracellular matrix production." (PMID 39170226, 2024). "To investigate the functional role of TMEM176B, we induced pulmonary fibrosis in mice using bleomycin, TGFβ1, and silica, which consistently resulted in a marked decrease in TMEM176B expression." (PMID 39170226, 2024). "Our study demonstrates that TMEM176B expression is significantly reduced in human and mouse pulmonary fibrosis, highlighting its potential role in the pathogenesis of the disease." (PMID 39170226, 2024). "Our analysis of GSE209929 identified a marked downregulation of Transmembrane Protein 176B (TMEM176B) in pulmonary fibrosis." (PMID 39170226, 2024). "Our study is, therefore, a significant contribution to this growing field, providing fresh insights into the role of TMEM176B in the progression of pulmonary fibrosis and setting the stage for future investigations." (PMID 39170226, 2024). "Overexpression of TMEM176B led to the reduction in collagen production, fibroblast proliferation and differentiation - key features of pulmonary fibrosis." (PMID 39170226, 2024). "The revelation, unearthed through diligent bioinformatics analysis using the GEO database, positions TMEM176B as a potential key player in the progression of pulmonary fibrosis." (PMID 39170226, 2024). "While our study provides valuable insights into the role of TMEM176B in pulmonary fibrosis, there are several limitations to consider." (PMID 39170226, 2024). "In our continued investigation of the potential beneficial role of TMEM176B in murine pulmonary fibrosis, we employed an adeno-associated viral vector (AAV) to overexpress TMEM176B (TMEM176B AAV)." (PMID 39170226, 2024). "Taken together, through the analysis of the GEO database, our study identified a significant downregulation of TMEM176B in pulmonary fibrosis and confirmed its highest expression in lung tissues, suggesting a potential role in the pulmonary fibrosis's progression." (PMID 39170226, 2024). "To investigate whether the ameliorative effect of TMEM176B on pulmonary fibrosis operates via the TGF-β-SMAD2/3 signaling, we utilized SB431542, an inhibitor of TGF-β." (PMID 39170226, 2024). "Moreover, our mechanistic evaluation indicated that TMEM176B appears to mitigate pulmonary fibrosis by inhibiting the TGFβ1-SMAD signaling pathway." (PMID 39170226, 2024). "Our findings have revealed a novel role for TMEM176B in the pathogenesis of pulmonary fibrosis." (PMID 39170226, 2024).
pulmonary fibrosis (continued). "Our study thus highlights TMEM176B as a potential anti-fibrotic actor, whose role could be harnessed to develop novel therapeutic strategies for pulmonary fibrosis." (PMID 39170226, 2024). "Modulating the levels or activity of TMEM176B could be a novel strategy to halt or even reverse the progression of pulmonary fibrosis." (PMID 39170226, 2024). "We induced pulmonary fibrosis in two distinct mouse groups using bleomycin, demonstrating successful overexpression of TMEM176B, which significantly attenuated the degree of fibrosis in the TMEM176B AAV group." (PMID 39170226, 2024). "To date, research specifically linking TMEM176B to pulmonary fibrosis is sparse." (PMID 39170226, 2024). "Therefore, TMEM176B may serve as a potential negative regulator of pulmonary fibrosis." (PMID 39170226, 2024). "The study has shown that TMEM176B can inhibit the TGFβ1-SMAD signaling pathway, which is critical for fibroblast proliferation, differentiation, and extracellular matrix production - key features of pulmonary fibrosis." (PMID 39170226, 2024).
squamous cell carcinoma (1 paper, 2024). A carcinoma arising from squamous epithelial cells. "The TMEM176B expression level did not affect the survival of patients with NSCLC or squamous cell carcinoma." (PMID 39001509, 2024).
Stroke (1 paper, 2012). Sudden impairment of blood flow to a part of the brain due to occlusion or rupture of an artery to the brain. "A number of new stroke-genes related to T- and dendritic cell activation and differentiation including Cd 8a, Tmem176b, Unc93b1, Vamp8, and Wipf1 also displayed persistent upregulation." (PMID 23251410, 2012).
systemic mastocytosis (1 paper, 2023). Systemic mastocytosis (SM) comprises a heterogeneous group of rare acquired and chronic hematological malignancies that are related to an abnormal proliferation of mast cells in tissue, including bone marrow, with or without skin involvement. "Notably, TMEM176B and CD52 were among the top 5 significant genes in all three datasets, with CD52 being reported as a marker of neoplastic MCs in patients with advanced systemic mastocytosis." (PMID 38031173, 2023).
tumor (26 papers, 2019 to 2026). "For instance, inhibitors of TMEM176B can enhance the antitumor efficacy of CD146+ tumor-associated macrophages." (PMID 40108613, 2025). "Transmembrane protein 176B (TMEM176B) is an immunoregulatory cation channel highly expressed in the tumor stroma in CRC patients, and it is associated with poor prognosis." (PMID 39684769, 2024). "In the tumor-draining lymph node of mice, Tmem176b deletion was associated with increased Caspase-1 activation in CD11b+ cDCs (cDC2) as well as with increased CD4+ RORγT+ cells versus WT animals." (PMID 36340035, 2022). "Particularly, TMEM176B expression was also linked to pathological stage, tumor ulceration and radiation therapy." (PMID 35399535, 2022). "TMEM176B expression levels, on the other hand, were significantly adversely associated with tumor purity." (PMID 35399535, 2022). "TMEM176B expression in tumor biopsies has also been associated with resistance to immune checkpoint blockers in melanoma patients." (PMID 36340035, 2022). "It suggests that TMEM176B plays an essential role in anti-tumor function of CD8+ T cells, but the underlying mechanisms need to be further investigated." (PMID 35399535, 2022). "The majority of tumor infiltrating lymphocytes (TILs) especially T cells in SKCM was positively linked with TMEM176B expression." (PMID 35399535, 2022). "Immune cells play an essential role in tumor immunity, however, to date, there are few reports on the association of TMEM176B with immune cells." (PMID 35399535, 2022). "In two other studies, inhibiting TMEM176B in tumor-associated cells was found to reduce tumor progression." (PMID 34943938, 2021). "Higher tumor stage and grade were associated with a lower TMEM176B protein level." (PMID 40108613, 2025). "Moreover, pharmacological targeting of TMEM176B mediates inhibition of tumor growth and increases susceptibility to immune checkpoint inhibition." (PMID 33584721, 2020). "Moreover, higher tumor stage and tumor grade were associated with a lower TMEM176B protein level." (PMID 40108613, 2025). "TMEM176B mRNA expression was significantly lower in OC tumor tissues compared to matched normal tissues." (PMID 40108613, 2025). "IHC analysis further revealed that the expression of TMEM176B in primary OC was markedly lower than that in normal ovarian tissue, and the expression was even lower after tumor metastasis." (PMID 40108613, 2025). "Subsequent clustering of tumor cells has pinpointed TMEM176B+ tumor cells as an indicator of ICB resistance." (PMID 41117057, 2025). "TMEM176B influences multiple cellular processes, such as cell proliferation, invasion, migration, and adhesion in vitro, as well as promoting tumor growth in vivo." (PMID 40108613, 2025). "The findings demonstrated a notable increase in TMEM176B expression in tumour tissues compared to their corresponding adjacent normal tissues." (PMID 39001509, 2024). "We conducted a xenograft tumor formation assay on athymic nude mice to validate the role of TMEM176B in GC progression." (PMID 38438907, 2024). "TMEM176B promoted cellular functions, including cell proliferation, invasion, migration and adhesion in vitro and tumour growth in vivo." (PMID 39001509, 2024). "Segovia and co-workers demonstrated that the inhibition of TMEM176B expression with BayK8644 triggered inflammasome activation and consequently limited tumor growth." (PMID 39684769, 2024). "The overexpression of TMEM176B not only affected cellular functions but also had an impact on in vivo tumour growth in CDX models." (PMID 39001509, 2024). "Using BayK8644 to inhibit TMEM176B markedly alleviated tumor growth in CD146 M-KO mice compared with M-WT mice." (PMID 37308559, 2023). "Additional outcomes revealed the expression of TMEM176A and TMEM176B was almost parallel followed by pseudo-time, and evidently elevated in tumor-infiltrating Mac2 and DC1 (logFC>1, P<0.01)." (PMID 37265785, 2023).
tumor (continued). "In this study, we clarified the relationship between CD146 and TMEM176B and combined them in tumor therapy, in which they showed great antitumor efficacy." (PMID 37308559, 2023). "The results of this part indicate that Tmem176b positively regulates the effector function and activation of tumor-infiltrating CD8+ T cells." (PMID 35399535, 2022). "At the same time deleting Tmem176b accelerated tumor progress and impaired T cells effector function." (PMID 35399535, 2022). "After tumor implantation, we tested the effect of deleting Tmem176b on T lymphocyte development and function in diverse tissues and immunological organs." (PMID 35399535, 2022). "Accordingly, high TMEM176B expression in the tumor infiltrate in human colon cancer correlates with poor survival." (PMID 36340035, 2022). "It revealed that suppressing inflammasomes by knocking down Tmem176b in mice or utilizing TMEM176B inhibitors can improve the anti-tumor effect of CD8+ T and the efficacy of anti-CTLA-4 and anti-PD1 therapy." (PMID 35399535, 2022). "Since the significant differential expression within tumor and normal tissues, we investigated the effect of TMEM176B expression on the prognosis of tumor patients." (PMID 35399535, 2022). "The tumor volume of mice following Tmem176b knockout was similarly greater and grew quicker than that of WT mice (p < 0.05)." (PMID 35399535, 2022). "In tumor-draining lymph nodes, Tmem176b expression in cDC2 was shown to be supported by regulatory T (Treg) CD4+ cells, suggesting an immunoregulatory role for this cation channels in cDC2." (PMID 36340035, 2022). "Increased TMEM176B protein levels have been found in various tumours, and inhibition of TMEM176B has been shown to increase CD8 + T cell-mediated tumour growth control, improving cancer therapy effectiveness." (PMID 36302939, 2022). "Overall, our results suggest that TMEM176B not only regulates the tumor immune microenvironment, as has been previously reported, but also directly affects cancer cells." (PMID 34943938, 2021). "We aimed to understand the role of TMEM176B in cancer cell signaling, gene expression, cell proliferation, and migration in vitro, as well as tumor growth in vivo." (PMID 34943938, 2021). "TMEM176B is a transmembrane protein that regulates the immune response of the tumor microenvironment." (PMID 34109215, 2021). "Syngeneic and xenograft tumor studies revealed the attenuated growth of tumors with TMEM176B gene silencing compared with controls." (PMID 34943938, 2021). "Within those tumors, TMEM176B knockout mice had a decreased abundance of immunosuppressive regulatory T cell molecules, and a higher percentage of total and tumor-specific CD8+ T cells compared with control mice." (PMID 34943938, 2021). "The whole-body deletion or pharmacological inhibition of TMEM176B in murine cancer models decreased tumor growth through enhanced anti-tumor T cell immunity and improved the response to immune checkpoint inhibitors." (PMID 34943938, 2021). "Inhibition of TMEM176B enhances tumor infiltration by CD8+ T cells and improves the antitumor activity of immune checkpoint blockers." (PMID 31085177, 2019). "Here, we show that disruption of transmembrane protein 176B (TMEM176B) contributes to CD8+ T cell-mediated tumor growth inhibition by unleashing inflammasome activation." (PMID 31085177, 2019). "Within the tumor microenvironment, CTLs from Tmem176b−/−Casp1−/− animals expressed lower levels of the degranulation marker CD107a than those from Tmem176b−/− mice." (PMID 31085177, 2019). "Together with our findings on TMEM176B and PD‐L1, these data suggest that thiol isomerase inhibition can reprogram the tumor microenvironment by disrupting both immune evasion and stromal activation, creating a milieu more permissive to immune clearance and less conducive to metastatic spread." (PMID 41474368, 2026).